IL33 (interleukin 33)
Diseases named in the same sentence as IL33 in open-access papers (continued):
Sharing a sentence is not in itself a finding about the gene and the disease.
Arthritis (continued). "Administration of IL-33 enhances allodynia in chronic constriction injury (CCI) mice whereas neutralizing IL-33 ameliorates hyperalgesia in arthritis, which suggests that IL-33 has a potential to contributes to pain status." (PMID 36287299, 2022). "Adoptive transfer of adequate ILC2s to arthritis models, in which the isolated cells were expanded in vitro through stimulation using cytokines such as IL-2, IL-7, IL-25, IL-33, and TSLP, mitigated experimental arthritis." (PMID 35163028, 2022). "IL33 has also been proposed to be a key molecule in arthritis; however, the expression of IL33 and its receptor ST2 in the articular cartilage of AVNFH are still unclear." (PMID 34305456, 2021). "In line with these human data, genetic deletion of ILC2 in mice aggravated K/BxN serum-induced arthritis whereas expansion of ILC2 by IL-25/IL-33 mini-circles or adoptive transfer of ILC2 from wild-type but not IL-4-/-IL-13-/- mice attenuated arthritis." (PMID 34733292, 2021). "In this study, we demonstrated that anti-IL-33 can reduce the severity of arthritis and the signs of joint injury in CIA mice after the onset of arthritis." (PMID 33490289, 2020). "In another recent study, genetic deletion of ILC2s in mice resulted in exacerbated arthritis, whereas increasing ILC2 number by IL-25/IL-33 mini-circles or adoptive transfer significantly attenuated arthritis by affecting the initiation phase." (PMID 32051038, 2020). "In line with the observed pathogenic role of GM-CSF in SpA, aggravation of arthritis and increased accumulation of GMP and neutrophils in inflamed joints induced by IL-33 injections were prevented if mice were co-injected with anti-GM-CSF." (PMID 31919358, 2020). "In the mouse model of RA, IL‐33 treatment markedly exacerbated arthritis and even erosion of cartilage." (PMID 32566227, 2020). "The activation and degranulation of mast cells under action of IL‐33 exacerbates arthritis and skin inflammation." (PMID 32566227, 2020). "In contrast, in arthritis and some other conditions, IL-33 serves as a pro-inflammatory cytokine and exacerbates inflammation and pain via promoting the production of TNF-α, CXCL1, IL-1β and PGE2 through ST2 in plantar skin tissues 37-39." (PMID 33204337, 2020). "In the present study, CIA mice were given intraperitoneally with polyclonal rabbit anti-murine IL-33 antibody (anti-IL-33) or normal rabbit IgG control after the first signs of arthritis." (PMID 33490289, 2020). "Clinically IL-33 injections twice weekly with 1 μg of IL-33 induced a significant worsening in the clinical score of arthritis and the joint swelling severity, which was also observed with a twofold lower dose of IL-33." (PMID 31919358, 2020). "In fact, budlein A ameliorates murine antigen-induced arthritis by inhibiting NF-κB activation and thereby Il-33, Tnf-α, Il-1β, endothelin-1, and Cox-2 mRNA expression in the knee joint." (PMID 30319413, 2018). "As previous works have reported that intra-articular injection of dsRNA led to the induction of arthritis, we next sought to investigate the role of IL-33 in the pathogenesis of a dsRNA-induced arthritic responses." (PMID 29095435, 2017). "IL-33 administration exacerbates collagen-induced and K/BxN serum-mediated murine arthritis, and disease severity is reduced in mice treated with sST2-Fc fusion protein or anti-IL-33 monoclonal antibody." (PMID 27964756, 2016). "And IL-33 expression was increased in inflammation parts of collagen-induced arthritis model in mice." (PMID 25032216, 2014). "We examined incidence and severity of K/BxN serum transfer-induced arthritis in IL-33 KO, ST2 KO and WT C57BL/6 mice." (PMID 23324173, 2013). "Here, we directly investigated the role of endogenous IL-33 in K/BxN serum transfer-induced arthritis by using IL-33 knockout (KO) mice." (PMID 23324173, 2013). "In fact, recent evidence suggests that IL-33 has the ability to polarize immune responses towards a Th17 profile in experimental models of arthritis." (PMID 23634226, 2013).
Arthritis (continued). "Two studies investigated involvement of IL-33 in the inflammatory effector phase of arthritis, as it can be studied in the K/BxN serum transfer-induced model." (PMID 23324173, 2013). "In the present study, we directly investigated the role of endogenous IL-33 in K/BxN serum transfer-induced arthritis using IL-33 KO mice and compared the results to those obtained using ST2 KO mice." (PMID 23324173, 2013). "In contrast, arthritis development and severity in IL-33 KO mice was similar to the disease observed in WT mice." (PMID 23324173, 2013). "The first study concluded to a pathogenic role of IL-33 based on reduced arthritis severity in ST2 KO mice and increased disease severity after injection of IL-33." (PMID 23324173, 2013). "The amount of IL-33 detected in different KBxN serum pools (n = 4) used for arthritis induction was 77 ± 31 pg/ml (range < 4.3 to 139 pg/ml)." (PMID 23324173, 2013). "In contrast, arthritis development and severity in IL-33 KO mice was still similar to that observed in WT controls." (PMID 23324173, 2013). "Transfer of purified arthritogenic IgG instead of complete K/BxN serum also resulted in similar arthritis severity in IL-33 KO and WT mice, excluding a contribution of IL-33 contained in the serum of donor mice to explain this result." (PMID 23324173, 2013). "K/BxN serum transfer induced pronounced arthritis with similar incidence and severity in IL-33 KO and wild-type (WT) mice." (PMID 23324173, 2013). "In K/BxN arthritis, the MC-dependent “flare” begins within minutes of serum administration, a timeframe probably too short for de novo IL-33 synthesis." (PMID 23071771, 2012). "To explore the role of IL-33 in K/BxN arthritis and to evaluate early immune complex-mediated activation of MCs, we induced arthritis in mice lacking ST2 as well as in WT control mice." (PMID 23071771, 2012). "The first study to link IL-33 expression with arthritis utilized in situ hybridization to show that IL-33 mRNA expression in the RA synovium is primarily in endothelial cells." (PMID 21871091, 2011). "In a model of anti-glucose-6-phosphate isomerase autoantibody-induced arthritis, IL-33 treatment exacerbated disease." (PMID 21871091, 2011). "These discrepancies suggest that IL-33 may have dual roles in arthritis, acting both as a proinflammatory mediator and as a regulator that promotes anti-inflammatory, Th2-skewed immune responses." (PMID 41087719, 2025). "Finally, we evaluated the efficacy of the mouse TLR9 antagonist ODN2088 in mitigating IL-33-induced arthritis in CAIA mice." (PMID 39617790, 2024). "In the study, blocking IL-33 in the spinal cord significantly alleviated hyperalgesia, paw swelling, and joint destruction, suggesting a role for IL-33 in the central inflammation mediated by astrocytes in arthritis animal models." (PMID 36387416, 2022). "It has been shown in a mouse model of collagen-induced arthritis that high expression of IL-25 is related to a regulatory mechanism in the presence of high levels of IL-17, and it has been found that IL-33 can intensify collagen-induced arthritis in experimental models." (PMID 34443554, 2021). "In contrast, the administration of IL-33 resulted in the exacerbation of arthritis." (PMID 34589505, 2021). "Moreover, an increased number of ILC2s that produced GM‐CSF in response to IL‐33 are found to initiate and augment arthritis." (PMID 32566227, 2020). "IL-33, another proinflammatory cytokine that was shown to exacerbate inflammation in preclinical arthritis models but that, at the same time, harbors direct effects on bone homeostasis, was significantly reduced in RA patients following short-term high-fiber dietary interventions." (PMID 33092271, 2020). "Moreover, IL-33 enhances autoantibody-mediated arthritis by promoting mast cell degranulation and proinflammatory cytokine production." (PMID 33490289, 2020). "However, other studies have shown that IL-33 appears to have an opposite effect on experimental arthritis." (PMID 33490289, 2020).
Arthritis (continued). "Although IL-33 apparently worsens arthritis and IL-33 blocking attenuates the disease progression in autoimmune conditions, the results of studies on IL-33 deficient mice indicate a rather modulating or even protective effect against the development of bone disease." (PMID 32069819, 2020). "Our data suggest that the treatment of arthritis with the IL-33-neutralizing antibody is a promising new method, which may help to prevent joint damage." (PMID 33490289, 2020). "Furthermore, injections of mice with recombinant IL-33 exacerbated disease pathology in autoantibody-induced and collagen-induced arthritis models, supporting a role for the IL-33/ST2 axis in models of autoimmunity." (PMID 30574145, 2018). "Indeed, IL-33 can orchestrate the influx of neutrophils and other immune cells subsidizing a dysfunctional joint inflammation in other arthritis models." (PMID 29867945, 2018). "We also investigated whether IL-10 is responsible for limiting IL-33/ST2 elicited joint inflammation in CIA." (PMID 28415811, 2017). "Clinical scoring revealed that the course of arthritis was similar in IL-33-/- and WT mice." (PMID 27317338, 2016). "Recently, a new study reported that endogenous IL-33 was not necessary for the development of joint inflammation in autoantibody-induced arthritis of IL-33-deficient mice." (PMID 25032216, 2014). "This implied that IL-33 exacerbates antigen-induced arthritis by acting on mast cells." (PMID 25032216, 2014). "A recent study proposed that during arthritis IL-33 released by synovial fibroblasts activates mast cells, which in turn, by their secretion of pro-inflammatory cytokines, could enhance IL-33 expression in the former, leading to a paracrine feed-forward loop." (PMID 24453940, 2014). "The treatment of mice with a soluble IL1RL1-Ig Fc fusion protein as decoy receptor or with a blocking anti-IL1RL1 antibody resulted in a reduction of the collagen induced arthritis and of the inflammatory response in the lung proving the therapeutic potential of the IL-33 and IL1RL1 interaction." (PMID 24503933, 2014). "Administration of sST2 which could neutralize IL-33 on collagen-induced arthritis in rats can reduce arthritis significantly, including reducing the clinical symptoms, synovial hyperplasia, and joint erosion." (PMID 25032216, 2014). "Several recent studies pointed to a crucial role of IL-33 during arthritis, which could promote joint inflammation, at least in part, by activating mast cells." (PMID 24453940, 2014). "Therefore, a contribution of IL-33 contained in the serum of K/BxN donor mice to arthritis severity in IL-33 KO recipient mice can be excluded." (PMID 23324173, 2013). "Therefore, to avoid co-injection of 'contaminating' IL-33 contained in the serum as a potential confounding factor, we thus used total IgG purified from K/BxN serum to induce arthritis." (PMID 23324173, 2013). "We explored the hypothesis that IL-33 enables participation of synovial MCs in murine K/BxN arthritis by promoting their activation by IgG immune complexes." (PMID 23071771, 2012). "However, our results suggest an alternate mechanism by which IL-33 contributes to acute MC activation in IgG-mediated arthritis." (PMID 23071771, 2012). "It therefore remains unclear, in the context of arthritis, whether the major role of IL-33 is to activate MCs directly or rather to potentiate their activation via other pathways, such as Fc receptors." (PMID 23071771, 2012). "Synovial cells are considered as the major source for IL-33 in arthritis." (PMID 22028860, 2011). "However, IL-33 deficiency did not influence disease severity in mouse models of K/B×N serum transfer-induced arthritis or CIA." (PMID 41087719, 2025). "Furthermore, a TLR9 antagonist reduced IL-33-induced arthritis in CAIA mice in vivo." (PMID 39617790, 2024).
Arthritis (continued). "In addition, induction of ILC2 by administration of IL-25/IL-33 accelerated the resolution of K/BxN serum-induced arthritis in wild-type but not eosinophil-deficient ΔdblGATA mice." (PMID 34733292, 2021). "IL-33 is an intermediate molecule in the crosstalk between mechanical stress and innate immune responses in articular cartilage, and may function as a previously unknown key target for the treatment of arthritis." (PMID 29095435, 2017). "IL-33 deficiency did not modify antigen-induced arthritis or CIA in DBA/1 mice." (PMID 27317338, 2016). "Indeed, mice deficient in the IL-33 receptor ST2 show reduced susceptibility to arthritis, and the disease is not modified in IL-33-deficient mice." (PMID 27317338, 2016). "Among these, we wanted to exclude a potential effect of IL-33 present in the injected serum, which might affect arthritis severity in IL-33-deficient, but not in ST2 receptor-deficient mice." (PMID 23324173, 2013). "Arthritis score correlated positively with iFABP levels and negatively with ileal CD8 + infiltration, IL-8, and IL-33 mRNA expression." (PMID 37280714, 2023). "Several studies suggested that IL-33 and ST2 are involved in the inflammatory process that leads to arthritis." (PMID 35401921, 2022). "They found that repeated injections of IL-33 during induction (early) and during development (late) of CIA strongly suppressed clinical and histological signs of arthritis." (PMID 33490289, 2020). "In animal studies, IL-33 exacerbates antigen-induced arthritis (AIA) and autoantibody-induced arthritis by activating mast cells." (PMID 33490289, 2020). "On a cellular and cytokine level, IVIg was reported to induce a Th2-type immune response with production of interleukin 33 (IL33) and IL4, leading to an increased expression of FcγRIIB on splenic macrophages in a murine arthritis model." (PMID 31244821, 2019). "With regard to experimental arthritis, the development and severity of CIA in IL-33 KO mice is comparable to that of WT mice." (PMID 30886947, 2017). "Some works suggest a functional role of the IL-33/ST2 axis in the pathogenesis of human and mouse arthritis." (PMID 27317338, 2016). "Previous work suggested implication of the IL-33/ST2 axis in the pathogenesis of human and mouse arthritis." (PMID 23324173, 2013). "Previous work suggested a functional role of the IL-33/ST2 axis in the pathogenesis of human and mouse arthritis." (PMID 23324173, 2013). "IL-33 can augment inflammation and potentiate the release of IL-1β and TNF-α in arthritis." (PMID 36287299, 2022). "In addition, a high level of IL33 induces the expression of inflammatory cytokines IL1-β, IL6, IL13, and IL17, as well as matrix metalloprotease- (MMP-) 3 and MMP-9 in arthritis." (PMID 34305456, 2021). "For example, repeated administration of IL-33 in the early and late stages of CIA mice models could relieve symptoms of arthritis." (PMID 34589505, 2021). "In a mouse model of methylated bovine serum albumin (mBSA)-induced arthritis, suppression of IL-33R (IL1RL1) expression in neutrophils could prevent IL-33-mediated neutrophil migration into the knee joint." (PMID 32719716, 2020). "Palmer of University of Geneva group found that arthritis development is not impaired in absence of endogenous IL-33 in AIA, CIA, and K/BxN serum transfer-induced model of arthritis." (PMID 33490289, 2020). "One study conducted on arthritis and Ps mouse models demonstrated that IL-33 was expressed in the synovium of arthritic mice, but it was not required for the development of arthritis." (PMID 31736655, 2019). "Therefore, the identification of IL-33 as a stimulus of MMP-1 and MMP-13, and the elucidation of its mechanisms of induction and action, provide new insights into the promotion of arthritis responses by the innate immune system." (PMID 29095435, 2017). "X-Gal staining of knee joints from IL-33-/- or WT IL-33+/+ mice was used to evaluate IL-33 promotor activity in mice with or without arthritis." (PMID 27317338, 2016).
Arthritis (continued). "Moreover, administration of IL-33 in human TNF-α transgenic mice, with spontaneous development of arthritis, inhibited bone destruction and reduced the number of osteoclasts." (PMID 27317338, 2016). "The data obtained with IL-33 KO mice indicate that endogenous IL-33 is not required for the development of joint inflammation in K/BxN serum transfer-induced arthritis." (PMID 23324173, 2013). "We wondered whether differences observed between IL-33 and ST2 KO mice regarding the severity of arthritis might be related to the existence of confounding variables in our experiment." (PMID 23324173, 2013). "In an attempt to determine whether reduced arthritis severity in ST2 KO mice might relate to a true IL-33 independent effect of ST2, we used blocking anti-ST2 antibodies to inhibit ST2 signaling during K/BxN serum transfer-induced arthritis." (PMID 23324173, 2013). "However, K/BxN serum transfer-induced arthritis is reduced in ST2-knockout mice but does not differ in IL-33-knockout and wild-type (WT) mice." (PMID 27317338, 2016). "We then examined in vitro bone resorption activity of mouse osteoclasts and showed that number of resorption spots and percentage resorption area were lower, but not significantly, in WT than IL-33-/- mice, especially when excluding mice without any arthritis from the analysis." (PMID 27317338, 2016). "In particular, the physical interaction of CCN3 with the IL33 cytokine combined with previous data indicating that CCN3 expression was regulated by TNFalpha and IL1 cytokines, point to CCN3 as a potent player in a variety of inflammatory responses, including neurodegenerative disease, and arthritis." (PMID 16895594, 2006). "However, the role of IL-33 could be paradoxical since, in K/BxN serum transfer-induced arthritis, ST2 but not IL-33 blockade may improve arthritis." (PMID 27964756, 2016). "A previous study described higher severity of K/BxN serum transfer-induced arthritis in C57BL/6, as compared to 129 WT mice, and we wondered whether carryover of genetic material from the original 129 strains might have affected arthritis severity in the IL-33 and ST2 lines used in this study." (PMID 23324173, 2013). "We confirm decreased severity of arthritis in ST2 KO, but not in IL-33 KO mice, suggesting that endogenous IL-33, although expressed in the synovium, is not required for the development of arthritis in this model." (PMID 23324173, 2013). "The lack of IL-33 involvement in our model of CIA confirms findings from studies of other models of RA, namely antigen-induced arthritis and CIA and K/BN serum transfer-induced arthritis." (PMID 27317338, 2016).